CDH1 (cadherin 1)
Diseases named in the same sentence as CDH1 in open-access papers (continued):
Sharing a sentence is not in itself a finding about the gene and the disease.
Hyperglycemia (15 papers, 2012 to 2025). An increased concentration of glucose in the blood. "The recruitment of SLUG to the CDH1 promoter was augmented by hyperglycemia, which was attenuated by silencing AKR1B1 and/or SORD." (PMID 38200154, 2024). "Hyperglycemia-induced CDH1 repression was rescued by YWHAH knockdown, and wild-type YWHAH, not the S25A mutant, repressed CDH1." (PMID 38200154, 2024). "In addition, L-fructose, which functionally competes with D-fructose, blocked hyperglycemia-induced cell migration and CDH1 suppression." (PMID 38200154, 2024). "Moreover, hyperglycemia-induced cytoskeletal rearrangement and CDH1 suppression were attenuated by AKR1B1 and/or SORD knockdown." (PMID 38200154, 2024). "Therefore, it is not surprising that the remarkable suppression of only CDH1 underlies the EMT induction by hyperglycemia." (PMID 38200154, 2024). "The initiation of EMT in HaCaT cells from hyperglycemia was confirmed by a morphological change, the increased expression of CDH2, KRT10, and ACTA2, and the downregulation of CDH1." (PMID 36827547, 2023). "The hyperglycemia-induced acquisition of metastatic potential was mediated by increased fructose derived from the polyol pathway, which stimulated the nuclear ketohexokinase-A (KHK-A) signaling pathway, thereby inducing EMT by repressing the CDH1 gene." (PMID 38200154, 2024). "In our study, CDH1 transcript expression was not changed in Ishikawa cells during hyperglycemia, but metformin-mediated upregulation occurred in the postmenopausal HEC-1A cell line at 1.0 mmol/L." (PMID 37313172, 2023).
pituitary adenomas (15 papers, 2010 to 2025). "With the same sample set, they demonstrated that it was possible to accurately discriminate invasive pituitary adenomas from non-invasive ones using the binary tree analysis on a group of genes including ESRP1, CDH1, and CTNNb1." (PMID 30733705, 2019).
ductal carcinoma in situ (14 papers, 1997 to 2025). "In a study with ductal breast carcinoma in situ, D’Arcy and coworkers depleted SDC1 in MCF10A cells and observed an upregulation of EMT marker gene expression, including E-cadherin (CDH1), fibronectin-1 (FN1), and claudin-1 (CLDN1)." (PMID 36980680, 2023).
prostate adenocarcinoma (14 papers, 2009 to 2025). "Our computational analysis identifies the miR-34a-5p/CDH1 axis as a novel regulatory mechanism in prostate adenocarcinoma, highlighting its potential as a biomarker and therapeutic target for EMT inhibition." (PMID 40693059, 2025). "While our integrated bioinformatics approach identified miR-34a-5p/CDH1 as a putative regulatory axis, we acknowledge the paradoxical upregulation of CDH1 (a canonical tumor suppressor) in prostate adenocarcinoma." (PMID 40693059, 2025). "Specifically, in human prostate adenocarcinomas, the down-regulation of the adhesion molecule CD44 standard (CD44s) and E-cadherin (CDH1) was reported to be associated with metastasis and high Gleason score." (PMID 29416676, 2018). "Our findings propose a novel regulatory loop involving miR-34a-5p/CDH1 in prostate adenocarcinoma, which may serve as a promising biomarker or a potential therapeutic target in future research." (PMID 40693059, 2025). "In addition, the effect of S100A4, ACKR3, and CDH1 expression on overall survival (OS) was assessed using the TCGA-prostate adenocarcinoma (PRAD) dataset." (PMID 31895690, 2019). "In this study, we aimed to identify EMT-related miRNA signatures in prostate adenocarcinoma through comprehensive bioinformatic analysis, validate their interactions with core EMT genes (e.g., CDH1, CDH2, SNAI1, ZEB1, ZEB2), and evaluate their potential as diagnostic or prognostic biomarkers." (PMID 40693059, 2025).
thyroid tumor (14 papers, 2012 to 2023). A benign or malignant neoplasm affecting the thyroid gland. "CDH1 and SCL5A8 promoter methylation are also associated with the carcinogenesis of thyroid tumor." (PMID 29723302, 2018). "Thus, our findings showed that CDH1 and SCL5A8 genes were associated with the risk of thyroid tumor genesis." (PMID 28926589, 2017). "Here, we report that the downregulation of NRP2 significantly induces CDH1 expression while inhibits all the mesenchymal markers that we tested, suggesting that this protein might represent a possible new target for preventing thyroid tumor invasion and metastasis." (PMID 26030152, 2015).
viral infection (14 papers, 2012 to 2025). "Our studies support a working model in which HCMV uses pUL97-mediated Cdh1 phosphorylation and pUL21a-mediated complex disruption to control APC activity for efficient virus infection." (PMID 22792066, 2012). "The protein levels of APC substrates Cdh1 (that is also an APC co-activator) and geminin were markedly increased in wild-type virus infection as previously reported." (PMID 22792066, 2012). "To confirm that decreased APC substrate accumulation during mutant virus infection was due to APC activity, we used shRNAs to knock down APC8 or the coactivator Cdh1 to deplete APC activity." (PMID 22792066, 2012).
acromegaly (13 papers, 2013 to 2025). Acromegaly is an acquired disorder related to excessive production of growth hormone (GH) and characterized by progressive somatic disfigurement (mainly involving the face and extremities) and systemic manifestations. "Tumor expression of particular genes was found of prognostic/predictive value in acromegaly patients, These genes include basically CDH1 and SSTR2 but also CDKN1B SNAI2, FLNA, ARRB1, SNAI1 RORC ESRP1, and MKI67." (PMID 39497133, 2024).
COVID-19 (13 papers, 2020 to 2025). A disease caused by infection with severe acute respiratory syndrome coronavirus 2. "Both E-cadherin and cadherin 11, together with β-catenin and p120 showed a normal expression pattern in alveolar epithelial cells and other epithelial cells in COVID-19 patients." (PMID 36405615, 2022). "Taken together, the decrease in the expression of CDH1, ACE2, and HMOX1 genes suggests that HBECs exposed to serum from the most severe COVID-19 patients (WHO-CPS = 9) acquire a dysfunctional and/or infected phenotype." (PMID 38494528, 2024). "The analysis of COVID-19 extended interactome indicates several membrane bound gene/proteins (i.e., ICAM1, EGFR, ERBB2, APP, ADR2, FAS, CDH1, and MAPT), whose activity and/or expression could be affected by SARS-CoV-2 challenge." (PMID 33123533, 2020).
hereditary cancer (13 papers, 2013 to 2024). Malignant neoplasms occurring in families at a rate greater than that expected by chance and caused by germline mutations in a specific gene. "Hereditary Diffuse Gastric Cancer (HDGC) syndrome is an autosomal dominant hereditary cancer predisposition associated with germline pathogenic/likely pathogenic variants in the CDH1 gene." (PMID 36056367, 2022). "Because only 5 CDH1 somatic alterations were found in paired peripheral blood, with only 1 supporting read for each, the potential for constitutional mosaicism, which is a well-known mechanism for multiple hereditary cancer–associated genes, was not supported in our data set." (PMID 36484990, 2022).
metastatic melanoma (13 papers, 2013 to 2025). A melanoma that has spread from its primary site to another anatomic site. "Except for the gene CDH1, all the hub genes were downregulated in metastatic melanoma tissues." (PMID 40722520, 2025).
acute myeloid leukemia (12 papers, 2015 to 2025). Acute myeloid leukemia (AML) is a group of neoplasms arising from precursor cells committed to the myeloid cell-line differentiation. "The significantly decreased Cdh1-expression in blasts of acute myeloid leukemia (AML) as compared to HSC may be a possible cause of their differentiation block." (PMID 35832196, 2022). "We found a significant decrease of Cdh1 in primary acute myeloid leukemia (AML) blasts compared to normal CD34+ cells." (PMID 27374082, 2016). "SUV39H1 inhibition is sufficient for re-expression of the silenced tumor suppressor genes CDKN2B and CDH1 marked by H3K9me3 in acute myeloid leukemia." (PMID 26840455, 2016). "For example, in patients with myelodysplastic syndrome (MDS) and acute myeloid leukemia (AML), azacytidine and DAC were used to demethylate tumor suppressor genes like CDH1 and CDNNA1, in order to achieve therapeutic effects." (PMID 33968756, 2021).
bladder tumors (12 papers, 2000 to 2025). "We observed hypermethylated CDH1, SFN, and RARB genes in the normal-adjacent tissue of urinary bladder tumor." (PMID 18702824, 2008).
brain tumors (12 papers, 2004 to 2024). "Pathogenic germline variants in other genes, e.g. POT1 and CDH1, more specifically increase the risk of a particular brain tumor, namely oligodendroglioma, among other tumors." (PMID 37990341, 2023). "In this study, we present data suggesting that heterozygous deactivating variants in the CDH1 gene increase the risk of brain tumors, primarily of ODs." (PMID 33929593, 2021). "The researchers report that CDH1 expression decreases with brain tumor grade." (PMID 39061990, 2024).
cleft lip (12 papers, 2014 to 2026). Congenital defect in the upper lip where the maxillary prominence fails to merge with the merged medial nasal prominences. "Patients with cleft lip have previously been shown to harbor variants in CDH1, while variants in CTNND1 are among the most common genetic causes of cleft lip in humans." (PMID 41231213, 2026). "Given the prominent role of p120-catenin in adherens junctions, and recent findings that show mutations in CDH1 in human cleft lip, we anticipated that E-cadherin, a core component of epithelial adherens complexes, would be required for lip fusion." (PMID 41231213, 2026). "Pathogenic variants of CDH1 gene have been implicated in syndromic and non-syndromic cleft lip-palate, as well as in hereditary diffuse gastric cancer." (PMID 37238140, 2023). "Approximately 1 in 5 families with germline CDH1 pathogenic variants identified a family member with cleft lip/palate." (PMID 36246616, 2022). "However, germline CDH1 mutations have also been identified in individuals with both sporadic and familial forms of cleft lip/palate." (PMID 32260281, 2020). "Recent studies indicated that patients with cleft lip had a higher incidence of tumors than the general population and, moreover, family members with pathogenetic CDH1 mutation showed a higher incidence of cleft lip/palate than the general population (6–7% versus about 0.1%)." (PMID 29295527, 2017). "The aim of this study was to evaluate the association between nucleotide variants of CDH1 and the risk of non-syndromic cleft lip with or without cleft palate (NSCL/P)." (PMID 24838934, 2014). "Family or personal history of cleft lip/palate, which is part of the HDGC syndrome due to CDH1, was reported by 12.7% (16/126) of patients." (PMID 37903316, 2024). "For the CDH1 gene, a PND case has been reported in a chinese mother and several fetuses displayed cleft lips with palate or other facial dysmorphic features." (PMID 37393258, 2023). "Previous studies indicate that CDH1, CTNND1, and MYH9 gene disruption may contribute to cleft lip in humans." (PMID 41231213, 2026).
endometrioid adenocarcinoma (12 papers, 2000 to 2024). An adenocarcinoma characterized by the presence of malignant glandular epithelial cells resembling endometrial cells. "Methylation of the CDH1 was reported as a prognostic marker in ovarian clear cell and endometrioid adenocarcinoma." (PMID 30653577, 2019).
periodontitis (12 papers, 2010 to 2025). An acute or chronic inflammatory process that affects the tissues that surround and support the teeth. "The periodontitis-affected gingival epithelium highly expressed tight junction genes claudin-1 (CLDN1) and E-cadherin (CDH1) (p < 0.001), while the average expression of occludin (OCLN) was also elevated, although this was not statistically significant." (PMID 41358003, 2025). "In an epigenetic study, hypermethylation of CpG islands in the CDH1 gene was detected in 25% of patients with chronic periodontitis, whereas no such hypermethylation was observed in healthy individuals." (PMID 40007608, 2025).
esophageal adenocarcinoma (11 papers, 1999 to 2023). A malignant tumor with glandular differentiation arising predominantly from Barrett mucosa in the lower third of the esophagus. "One study focusing solely on esophageal adenocarcinomas showed that the chemoresistance was conveyed through alteration of the Wnt/β-catenin pathway and DKK2, CDH1, CD44, MYC, and ABCG2 expression." (PMID 31467538, 2019).
listeriosis (11 papers, 2010 to 2025). A bacterial infection caused by Listeria monocytogenes. "In contrast to the Cdh1 transgenic mouse models, this mouse model permits the analysis of orally acquired listeriosis without the need to cross in ‘humanized’ alleles of Cdh1." (PMID 23617550, 2013).
lymphoma (11 papers, 2005 to 2023). A malignant (clonal) proliferation of B- lymphocytes or T- lymphocytes which involves the lymph nodes, bone marrow and/or extranodal sites. "Although the age-related increased incidence was not statistically significant (p = 0.07 in controls, p = 0.48 in Cdh1+/- mice), the spontaneous development of lymphoma in aged C57BL/6J mice is common." (PMID 35361739, 2022). "The incidence of lymphoma was similar in both cohorts (p = 1.00), and this made it difficult to detect an increase in B-cells or T-cells in the prostates of Cdh1+/- mice compared to age-matched controls at 24 months of age." (PMID 35361739, 2022). "Tumors regenerated, like p16−/− primary tumors, were predominantly composed of lymphoma cells mixed with Cdh1-positive and Ck14-negative tumor cells (and data not shown)." (PMID 27811360, 2016). "The LRP12 and CDH1 genes have a great potential as DNA methylation biomarkers for lymphoma, since these were able to discriminate with a high sensitivity and specificity lymphoma patients from the various control samples and follicular hyperplasia." (PMID 25226156, 2014). "The lymphoma patients included in the test series showed methylation frequencies of 93%, 90% and 60% for CDH1, LRP12 and BMPER, respectively." (PMID 25226156, 2014). "The combination of LRP12 and CDH1 methylation could successfully discriminate between the vast majority of the lymphoma and control samples, emphasized by receiver operating characteristic analysis with a c-statistic of 0.999." (PMID 25226156, 2014). "The promoter methylation of LRP12, CDH1, BMPER and DUSP4 was 100%, 91%, 55%, and 32% across all analyzed lymphoma types included in the validation series, respectively." (PMID 25226156, 2014). "For BMPER, CDH1 and LRP12 statistically significant differences in the PMR values were seen between several of the lymphoma groups analyzed, as well as in comparison with the control samples." (PMID 25226156, 2014). "Taken together, we identified several genes (BMPER, BMP7, CDH1, DUSP4 and LRP12) which were frequently methylated in major lymphoma types." (PMID 25226156, 2014). "Further, similar to our findings, the positive correlations between E-cadherin (CDH1) and ADAMTS18 mRNA levels were found in human lymphoma samples, which may reflect the requirement of ADAMTS18 for E-cadherin processing in the cells." (PMID 28145888, 2017). "Of the nine p16−/− tumors, two were detected in the mammary gland and were highly composed of lymphoma cells, as evidenced by their lymphocyte-like morphology, positivity for CD45 and CD31 by FACS analysis and negativity for Cdh1, an epithelial cell marker, by IHC." (PMID 27811360, 2016). "A small portion of epithelial-like cells observed in two primary p16−/− lymphomas that developed in mammary glands were sporadic and cuboid, luminal-like cells that were negative for Ck14 and positive for Cdh1." (PMID 27811360, 2016). "In a future perspective, the hypermethylated CDH1 and LRP12 gene promoters could be used in a blood-based test to differentiate lymphoma patients from healthy donors and follicular hyperplasia." (PMID 25226156, 2014). "Therefore, considering that these heritable alterations could be maintained also after the loss of the virus, we investigated the methylation pattern of the CDH1 and MGMT gene promoters in whole lymphoma tissue sections." (PMID 32483241, 2020).
pituitary tumor (11 papers, 2013 to 2025). A benign or malignant neoplasm affecting the pituitary gland. "Likewise, the methylation status of the CDH1 gene is also responsible for gene silencing in certain pituitary tumors." (PMID 29267504, 2017).
serous ovarian cancer (11 papers, 2015 to 2025). "The less-aggressive serous carcinoma with low malignant potential has significantly higher CDH1 expression compared with high-grade serous ovarian cancer (p = 4.12E-08)." (PMID 26549805, 2015). "We drew the heatmap plot to classify the up-regulated and down-regulated analyzed genes including integrins, CDH-1, CDH-2, and Wnt5A in different subtypes of serous ovarian cancer and normal ovary." (PMID 33723319, 2021).
carcinoma in situ (10 papers, 2005 to 2024). "The inactivation of the second CDH1 allele (e.g., the gene encoding E-cadherin) leads to the appearance of an in situ carcinoma, with the presence of signet-ring cells with a “Pagetoid” pattern of diffusion, which is subsequently followed by the invasion of surrounding tissues." (PMID 22778942, 2012).
endometrial adenocarcinoma (10 papers, 2012 to 2025). "In this study, the results showed that the expression of miR-543 was negatively correlated with the expression of CDH2 and positively correlated with the expression of CDH1 in endometrial epithelial cells and endometrial adenocarcinoma cells." (PMID 33860034, 2021). "In endometrial epithelial cells and endometrial adenocarcinoma cells, after the overexpression of miR-543, the mRNA expression of vimentin, COL16A1, α-SMA, and Fibronectin decreased, while the mRNA expression of CDH1 increased, while miR-543 inhibitor played the opposite role." (PMID 33860034, 2021).
intestinal tumors (10 papers, 2008 to 2025). "A role for E-cadherin in tumorigenesis is underscored by the increased intestinal tumour burden in Apc+/1638N/Cdh1 +/- mice compared to mice with the Apc+/1638N mutation." (PMID 33057364, 2020).
kidney cancer (10 papers, 2015 to 2025). Primary or metastatic malignant neoplasm involving the kidney. "Here, we analyzed the SUMOylation-related gene expression status at the RNA level in kidney cancer tissues and built a risk model using three SUMOylation genes, CDH1, CDCA8, and PPARA, to indicate the outcomes based on differentially expressed SUMOylation genes." (PMID 37201027, 2023). "The only exception to this trend was kidney cancer, which exhibited significantly lower levels of CDH1 mRNA and E-cad protein, the pattern normally described in textbooks." (PMID 37189027, 2023). "At the RNA level, CDCA8 was overexpressed, while CDH1 and PPARA were downregulated in kidney cancer tissues, in TCGA-KIRC." (PMID 37201027, 2023). "In addition, three genes (CDCA8, CDH1, and PPARA) presented as independent factors of kidney cancer by multivariate cox regression." (PMID 37201027, 2023). "For the patients with carcinomas that had downregulated CDH1 mRNA, including kidney cancer, CDH1 mRNA expression had a significant effect on OS but not DFS (High, n = 258 vs Low, n = 258; p = 3.7E-06 and 0.11, respectively)." (PMID 37189027, 2023).